SLC7A11 (solute carrier family 7 member 11)
Diseases named in the same sentence as SLC7A11 in open-access papers (continued):
Sharing a sentence is not in itself a finding about the gene and the disease.
colon cancer (34 papers, 2021 to 2025). "In conclusion, these findings suggest that the suppression of IGF2BP3 in colon cancer cells drives ferroptosis through the modulation of SLC7A11 mRNA stability, consequently increasing the susceptibility to ferroptosis." (PMID 40530014, 2025). "Despite not preventing elesclomol-induced RCD, the combined treatment of elesclomol and Cu in colon cancer cells results in the accumulation of reactive oxygen species and the degradation of solute carrier family 7 member 11 (SLC7A11), which is closely linked to ferroptosis." (PMID 38164173, 2024). "A notable decline in the mRNA expression of SLC7A11 was detected in colon cancer cells following the knockdown of IGF2BP3." (PMID 40530014, 2025). "In conclusion, our study reveals that IGF2BP3 regulates ferroptosis in colon cancer cells through SLC7A11, and miR-98-5p modulates ferroptosis in colon cancer cells by interacting with IGF2BP3." (PMID 40530014, 2025). "Targeting the miR-98-5p/IGF2BP3/SLC7A11 axis offers a promising therapeutic strategy to enhance ferroptosis sensitivity and improve colon cancer outcomes." (PMID 40530014, 2025). "IGF2BP3 drives ferroptosis resistance in colon cancer by stabilizing SLC7A11 mRNA, while miR-98-5p antagonizes this pathway via IGF2BP3 downregulation." (PMID 40530014, 2025). "Studies on AP003555.1 primarily examined the link between ferroptosis and colon cancer, concentrating on the potential role of SLC7A11-mediated cystine absorption in inhibiting ferroptosis." (PMID 39115621, 2024). "The results showed that the most disulfidptosis associated genes was upregulated except SLC7A11 and SLC3A2, which confirmed the involvement of disulfidptosis in colon cancer." (PMID 38802854, 2024). "All these findings indicate that SLC7A11 plays an important role in the ferroptosis of colon cancer cells." (PMID 36846715, 2023). "Then, we knocked down SLC7A11 by small interfering RNAs (siRNAs) and found that depletion of SLC7A11 reduced cystine-mediated cell growth in both colon cancer cell lines." (PMID 34045438, 2021). "Moreover, curcumin down-regulates the protein expression of GPX4 and Solute carrier family 7 member 11 (SLC7A11) to induce ferroptosis in colon cancer (HCT-8) and follicular thyroid cancer (FTC-133 and FTC-238) cells." (PMID 40490812, 2025). "The key ferroptosis regulator, SLC7A11, is overexpressed in colon cancer cells and tissues." (PMID 40221412, 2025). "Based on this, we hypothesize that MSL1 induces ferroptosis via SLC7A11 suppression, potentially inhibiting colon cancer progression through its interacting with KCTD12." (PMID 40221412, 2025). "Ultimately, we identified that IGF2BP3 may regulate ferroptosis in colon cancer cells through its interaction with SLC7A11." (PMID 40530014, 2025). "In addition, RSV can induce iron death in colon cancer cells by promoting lipid peroxidation and inhibiting the protein expression of SLC7A11 and GPX4." (PMID 40490812, 2025). "Finally, we collected 20 pairs of colon cancer and paracancer tissues and observed a high expression of SLC7A11 in colon cancer tissues." (PMID 36846715, 2023). "It is possible that CREB up-regulation of SLC7A11 also play a carcinogenic role in colon cancer." (PMID 35174151, 2022). "Thus, targeting SLC7A11 is a promising strategy for colon cancer therapy." (PMID 40221412, 2025). "Indeed, in both breast and colon cancer cells, KCTD10 knockdown caused the accumulation of endogenous SLC7A11, whereas KCTD10 overexpression reduced the levels of endogenous SLC7A11 in a dose-dependent manner." (PMID 38959043, 2024).
colon cancer (continued). "Collectively, these findings demonstrate that the MSL1-KCTD12 axis regulates SLC7A11 and GPX4, thereby modulating Erastin-induced ferroptosis in colon cancer cells." (PMID 40221412, 2025). "Mechanistically, gallic acid regulates the ferroptosis of colon cancer cells by upregulating the ferroptosis-inducing ATF4 gene and downregulating ferroptosis-inhibiting genes (GPX4 and SLC7A11)." (PMID 38892270, 2024). "Matrine shows antiproliferation and promotes the ferroptosis of colon cancer cells by upregulating the ferroptosis-inducing ATF4 gene and downregulating the ferroptosis-inhibiting genes (GPX4 and SLC7A11)." (PMID 38892270, 2024). "Talaroconvolutin A, a Talaromyces purpureogenus-derived natural product, inhibits proliferation and promotes the ferroptosis of colon cancer cells by upregulating the ferroptosis-inducing ALOXE3 gene and downregulating SLC7A11." (PMID 38892270, 2024). "Furthermore, we found that MSL1 downregulation, via modulation of KCTD12, suppresses the expression of key negative regulators of ferroptosis, SLC7A11 and GPX4, thereby promoting Erastin-induced ferroptosis in colon cancer cells." (PMID 40221412, 2025). "Furthermore, in LPCAT2 knockout mice (LPCAT2−/−) colon cancer model, we found that LPCAT2−/− mice exhibited more severe lesions, while PRMT1 or SLC7A11 inhibitors delayed the progression." (PMID 38605214, 2024). "SLC7A11, a component of the xCT system, which mediates cystine uptake and glutamate release to promote GSH synthesis, an upstream process of ferroptosis, is highly expressed in colon cancer." (PMID 37273145, 2023). "To critically determine the functional role of selenite-mediated up-regulation of SLC7A11, we evaluated effect of SLC7A11 inhibition by its chemical inhibitor or knocking-down of SLC7A11 on selenite/glucose deprivation-induced cytotoxicity in HCT116 colon cancer cells." (PMID 35053507, 2022).
liver fibrosis (31 papers, 2021 to 2025). "SLC7A11 imports extracellular cystine for GSH synthesis, and its loss lowers GSH levels; in liver fibrosis, SLC7A11 inhibition increases ferroptosis in hepatic stellate cells." (PMID 40883748, 2025). "In summary, evidence on the role of SLC7A11 in PF is scarce relative to the evidence of its role in liver fibrosis; however, SLC7A11 downregulation in the lung is associated with PF." (PMID 40249927, 2025). "We examine the effects of SLC7A11 on liver cells or HSCs, and the interactions between different cell types mediated by SLC7A11, focusing on its role in liver fibrosis." (PMID 40249927, 2025). "HIF-1α/SLC7A11 was involved in sorafenib attenuating liver fibrosis by triggering hepatic stellate cell ferroptosis." (PMID 40935814, 2025). "SLC7A11 influences liver fibrosis through several mechanisms, presumably because of its diverse functions in different cell types." (PMID 40249927, 2025). "Recent studies have shown that traditional Chinese medicine berberine inhibits liver fibrosis by inducing ferroptosis in HSCs by inhibiting the SLC7A11/GPX4 axis." (PMID 40524220, 2025). "SLC7A11 upregulation in hepatocytes can reduce liver fibrosis directly or by inhibiting HSC activation through inflammatory factors, thereby having a beneficial effect." (PMID 40249927, 2025). "The development of SLC7A11-targeting drugs for the treatment of liver fibrosis treatment is an exciting avenue for future research." (PMID 40249927, 2025). "In the liver, SLC7A11 controls the progression of liver fibrosis by reducing ECM production through the inhibition of hepatocyte ferroptosis and mitochondrial autophagy." (PMID 40249927, 2025). "Current studies have identified that SLC7A11 can influence the progression of liver fibrosis through mitophagy." (PMID 40249927, 2025). "Building upon prior evidence that FN mitigates renal fibrosis through SMAD3/ATF3/SLC7A11 pathway inhibition, we extended these observations to hepatic fibrosis using comprehensive analyses." (PMID 40852727, 2025). "The development of drugs aimed at targeting SLC7A11 for treating liver fibrosis is in its preliminary stages." (PMID 40249927, 2025). "In a mouse NASH model, liver fibrosis was markedly more pronounced in SLC7A11 knockout mice than in their wild-type counterparts under identical conditions, whereas SLC7A11 overexpression in mouse hepatocytes ameliorated liver fibrosis." (PMID 40249927, 2025). "Targeting SLC7A11 to induce ferroptosis in HSCs and mitigate the accumulation of fibrosis-related substances in the liver can be used to address liver fibrosis." (PMID 40249927, 2025). "TRIM26 can attenuate SLC7A11 activity and promote ferroptosis in HSCs through SLC7A11 ubiquitination, thereby reducing liver fibrosis." (PMID 40249927, 2025). "The intricate interplay between SLC7A11 and various liver tissue cells contributes to the complexity of liver fibrosis." (PMID 40249927, 2025). "For instance, TRIM26 induces HSC ferroptosis to inhibit liver fibrosis by the ubiquitinated degradation of SLC7A11." (PMID 38756248, 2024). "The direct role of miR-26a/SLC7A11 axis in liver fibrosis can be investigated both in vitro and in vivo." (PMID 38756248, 2024). "In both in vivo and in vitro studies, mesenchymal stem cell-derived exosomal miR-26a was shown to inhibit HSCs activation by downregulating SLC7A11 expression, thereby promoting ferroptosis in HSCs and mitigating liver fibrosis." (PMID 39717848, 2024). "A SLC7A11 knockdown together with miR-26a treatment can be conducted to further confirm that miR-26a control liver fibrosis through the SLC7A11 pathway." (PMID 38756248, 2024). "SLC7A11 has been demonstrated to have potentially therapeutic effects in preventing or treating liver fibrosis." (PMID 38756248, 2024). "In summary, our results expounded that BMSC-derived exosomal miR-26a induced ferroptosis to alleviate liver fibrosis by regulating SLC7A11." (PMID 38756248, 2024).
liver fibrosis (continued). "Ferroptosis is triggered by tripartite motif‐containing protein 26, which inhibits liver fibrosis and hepatic steatosis by ubiquitinating SLC7A11." (PMID 36655094, 2023). "Curcumol, ellagic acid, wogonoside, decursin, sorafenib, berberine, celastrol, isoliquiritigenin, DHA, WBME, and chrysophanol alleviate liver fibrosis through inducing ferroptosis by inhibiting SLC7A11." (PMID 36703745, 2022). "TRIM26 can inhibit liver fibrosis by mediating the ubiquitination of SLC7A11 and promoting the ferroptosis of hepatic stellate cells (HSCs), which can be used as a new therapeutic strategy for liver fibrosis." (PMID 35478955, 2022). "In this study, we provide evidence that sorafenib ameliorates CCl4‐induced liver fibrosis by triggering ferroptosis in HSCs through HIF‐1α/SLC7A11 pathway." (PMID 34811833, 2022). "Sorafenib triggers hepatic stellate cell ferroptosis by inhibiting the HIF‐1α/SLC7A11 pathway to attenuate liver fibrosis." (PMID 34811833, 2022). "A recent study demonstrated that liraglutide can alleviate liver fibrosis by inhibiting hepatocyte ferroptosis through upregulating SLC7A11 expression and the Nrf2/HO-1/GPX4 pathway." (PMID 36703745, 2022). "Although the functions of TRIM26 in other forms of HSCs programmed cell death need to be further investigated, the findings from the current study provide novel insights on an SLC7A11-targeted therapeutic approach for hepatic fibrosis." (PMID 33869196, 2021). "Our findings propose that TRIM26-induced SLC7A11 suppression can be potentially targeted for liver fibrosis treatment." (PMID 33869196, 2021). "In conclusion, TRIM26 promotes HSCs ferroptosis to suppress liver fibrosis through mediating the ubiquitination of SLC7A11." (PMID 33869196, 2021). "For example, upregulation or downregulation of SLC7A11 expression in liver fibrosis may yield different outcomes, and similar mechanisms may exist in other organs." (PMID 40249927, 2025). "Targeting SLC7A11 in the treatment of chronic liver injury fails to alleviate liver fibrosis and exacerbates hepatic damage, increasing markers associated with liver fibrosis." (PMID 40249927, 2025). "The involvement of SLC7A11 in liver fibrosis extends beyond its effects on ferroptosis." (PMID 40249927, 2025). "Furthermore, we explore the potential for developing SLC7A11-targeted therapeutics for liver fibrosis, and the future directions for research on the effect of SLC7A11 on liver fibrosis." (PMID 40249927, 2025). "Targeting SLC7A11 to induce HSCs ferroptosis can ameliorate liver fibrosis." (PMID 40249927, 2025). "Conversely, SLC7A11 downregulation in HSCs to induce ferroptosis also reduces liver fibrosis." (PMID 40249927, 2025). "Further investigation into how SLC7A11 affects fibrosis at the cellular, organ, and immune system levels is crucial for developing targeted therapies, particularly for liver fibrosis, and advancing our understanding of its potential as a therapeutic target in fibrotic diseases." (PMID 40249927, 2025). "In a mouse model of liver fibrosis induced by C-C Motif Chemokine Ligand 4 (CCL4), exosomes derived from mesenchymal stem cells (MSCs) carrying miR-26a were shown to promote ferroptosis in hematopoietic stem cells (HSCs) and regulate SLC7A11 expression, thereby alleviating liver fibrosis." (PMID 40191227, 2025). "Thus, SLC7A11 overexpression in hepatocytes protects against the development of liver fibrosis by regulating hepatocytes, inhibiting inflammatory factor production, and reducing activated HSCs." (PMID 40249927, 2025). "SLC7A11 can promote ferroptosis in HSCs and ameliorate liver fibrosis." (PMID 40249927, 2025). "Sorafenib evokes HSC ferroptosis to attenuate liver fibrosis by regulating the HIF-1α/SLC7A11 axis." (PMID 38756248, 2024).
liver fibrosis (continued). "Collectively, miR-26a mimic-Exo induced ferroptosis to alleviate liver fibrosis by regulating SLC7A11, which may provide new strategies for the treatment of liver fibrosis, and even other relevant diseases." (PMID 38756248, 2024). "However, a CCl4‐induced liver fibrosis animal model inhibiting xCT/SLC7A11 exacerbates chronic liver damage while killing myofibroblastic HSCs in the liver." (PMID 36655094, 2023). "TRIM26 is another E3 ubiquitin ligase that physically interacts with SLC7A11 and that mediates its ubiquitination, it increases the lipid peroxidation and the ferroptosis of hepatic stellate cells through SLC7A11 degradation, finally inhibits liver fibrosis." (PMID 37190313, 2023). "Furthermore, TRIM26 protects against hepatic stellate cell activation and thereby alleviates the progression of hepatic fibrosis by mediating SLC7A11 ubiquitination and ferroptosis." (PMID 37821436, 2023). "Trim26 promotes HSC ferroptosis in liver fibrosis by mediating SLC7A11 ubiquitination to inhibit liver fibrosis, which may be a new treatment strategy." (PMID 36276287, 2022). "Moreover, sorafenib was shown to attenuate liver fibrosis by triggering HSCs ferroptosis via hypoxia-inducible factor (HIF)-1α/SLC7A11 signaling in a carbon tetrachloride (CCl4)-induced mouse liver fibrosis model." (PMID 36703745, 2022). "Studies have shown that inhibiting the expression of SLC7A11 could induce ferroptosis in HSCs and alleviate liver fibrosis." (PMID 35720113, 2022). "The TRIM26-targeted SLC7A11 suppression can be a novel therapeutic strategy for liver fibrosis." (PMID 33869196, 2021). "It was previously reported that inhibiting SLC7A11 in HSCs could induce the ferroptosis of myofibroblasts and attenuate liver fibrosis." (PMID 33869196, 2021). "Furthermore, we also demonstrate that TRIM26 overexpression in mice can suppress SLC7A11 and effectively mitigate CCl4-induced liver fibrosis." (PMID 33869196, 2021). "Therefore, SLC7A11 suppression possesses potential therapeutic functions in preventing or treating hepatic fibrosis." (PMID 33869196, 2021). "Several agents that may target SLC7A11 in HSCs have been proposed to treat liver fibrosis." (PMID 40249927, 2025). "Moreover, SLC7A11 overexpression could potentially safeguard against the progression of liver fibrosis by suppressing the inflammatory response and reducing HSC activation." (PMID 40249927, 2025). "Notably, in vivo overexpression of TRIM26 in livers significantly mitigates carbon tetrachloride-induced liver fibrosis progression by suppressing hepatic stellate cells (HSCs) hyperactivation via degradation of solute carrier family-7 member-11 (SLC7A11) and promotion of HSCs ferroptosis." (PMID 37821436, 2023). "SLC7A11 activity is crucial for MF-HSC function, and the promotion of HSC ferroptosis reduces liver fibrosis." (PMID 40249927, 2025). "Further, SLC7A11 plays a vital role in the pathogenesis of HCC, including liver damage, chronic inflammation, hepatocyte proliferation, liver fibrosis and cirrhosis, disorganized vasculature, and modulations of the liver's immune microenvironment." (PMID 39744233, 2025). "Wogonoside activated ferroptosis by decreasing the levels of solute carrier family 7 member 11 (SLC7A11), GPX4, and GSH in mouse HSC-T6 cells, while reducing the levels of α-smooth muscle actin (α-SMA) with COL1A1 and alleviating liver fibrosis." (PMID 40278581, 2025). "The GSH, GPX4 and SLC7A11 expression were decreased and ferroptosis was activated in CCl4-induced liver fibrosis mice, but the GPX4 and SLC7A11 expression were increased and ferroptosis signature was attenuated in LX-2 cells treatment with LPS." (PMID 40278581, 2025). "Downregulation of SLC7A11 induces HSC ferroptosis, accompanied by an improvement in liver fibrosis through various mechanisms." (PMID 40249927, 2025).